ATG16L1 (autophagy related 16 like 1)
Description:
Plays an essential role in both canonical and non-canonical autophagy: interacts with ATG12-ATG5 to mediate the lipidation to ATG8 family proteins (MAP1LC3A, MAP1LC3B, MAP1LC3C, GABARAPL1, GABARAPL2 and GABARAP). Acts as a molecular hub, coordinating autophagy pathways via distinct domains that support either canonical or non-canonical signaling. During canonical autophagy, interacts with ATG12-ATG5 to mediate the conjugation of phosphatidylethanolamine (PE) to ATG8 proteins, to produce a membrane-bound activated form of ATG8. Thereby, controls the elongation of the nascent autophagosomal membrane. As part of the ATG8 conjugation system with ATG5 and ATG12, required for recruitment of LRRK2 to stressed lysosomes and induction of LRRK2 kinase activity in response to lysosomal stress (By similarity). Also involved in non-canonical autophagy, a parallel pathway involving conjugation of ATG8 proteins to single membranes at endolysosomal compartments, probably by catalyzing conjugation of phosphatidylserine (PS) to ATG8. Non-canonical autophagy plays a key role in epithelial cells to limit lethal infection by influenza A (IAV) virus (By similarity). Regulates mitochondrial antiviral signaling (MAVS)-dependent type I interferon (IFN-I) production. Negatively regulates NOD1- and NOD2-driven inflammatory cytokine response. Instead, promotes an autophagy-dependent antibacterial pathway together with NOD1 or NOD2. Plays a role in regulating morphology and function of Paneth cell.
Synonyms: APG16L; WDR30; FLJ10035; ATG16A; ATG16L; IBD10
Tractability: Small molecule: a structure with a bound ligand is known. Antibody: UniProt places it where antibodies can reach, with high confidence. PROTAC: ubiquitination databases record sites on it; its protein half-life has been measured.
Gene: Protein-coding gene on chromosome 2 (233,210,051 to 233,295,674, forward strand). Ensembl gene ENSG00000085978.
Subcellular location: Cytoplasm; Preautophagosomal structure membrane; Endosome membrane; Lysosome membrane
Subcellular location (Human Protein Atlas): Cytosol; Equatorial segment; Mid piece; Principal piece
Pathways (Reactome):
Autophagy: Macroautophagy
Gene Ontology:
Molecular function: GTPase binding; identical protein binding; protein binding; protein-membrane adaptor activity; ubiquitin-like protein transferase activity
Biological process: autophagosome assembly; C-terminal protein lipidation; macroautophagy; microautophagy; protein localization to phagophore assembly site; axonal transport; defense response to virus; positive regulation of autophagy
Cellular component: Atg12-Atg5-Atg16 complex; autophagosome membrane; cytoplasm; cytosol; endolysosome membrane; endosome membrane; lysosomal membrane; phagophore assembly site membrane; vacuole-isolation membrane contact site; autophagosome; axoneme; sperm midpiece; axon; glutamatergic synapse
Genetic constraint (gnomAD): Loss-of-function variants: 34 observed, 83.02 expected, observed/expected ratio (o/e) 0.41, 90% interval 0.31 to 0.55. The upper end of that interval is the gene's LOEUF score, 0.55, which puts it in group 2 of 6, group 1 being the genes least tolerant of losing a copy. Missense variants: 515 observed, 717.24 expected, observed/expected ratio (o/e) 0.72, 90% interval 0.67 to 0.77. Synonymous variants: 282 observed, 268.28 expected, observed/expected ratio (o/e) 1.05, 90% interval 0.95 to 1.16.
Homologues: Orthologues: chimpanzee ATG16L1 (99% identical), macaque ATG16L1 (99% identical), dog ATG16L1 (95% identical), guinea pig ATG16L1 (94% identical), mouse Atg16l1 (94% identical), rat Atg16l1 (94% identical), pig ATG16L1 (94% identical), rabbit ATG16L1 (94% identical), tropical clawed frog atg16l1 (80% identical), zebrafish atg16l1 (74% identical), Drosophila melanogaster Atg16 (39% identical), Caenorhabditis elegans atg-16.1 (27% identical), and 1 more. Paralogues in human: ATG16L2 (38% identical).
Diseases named in the same sentence as ATG16L1 in open-access papers:
ATG16L1 is named in the same sentence as 170 diseases in open-access papers, as found by Europe PMC text mining. Sharing a sentence is not in itself a finding about the gene and the disease. The quoted sentences say what the papers report.
Crohn disease (144 papers, 2008 to 2026). A gastrointestinal disorder characterized by chronic inflammation involving all layers of the intestinal wall, noncaseating granulomas affecting the intestinal wall and regional lymph nodes, and transmural fibrosis. "IBDs, including UC and Crohn’s disease, are characterized by autophagy pathways, with autophagy-related genes (ATG16L1, immunity-related GTPase M) identified as the susceptibility loci." (PMID 41487454, 2026). "Macroautophagy/autophagy exerts multilayered protective functions in intestinal epithelial cells (IECs) while a loss-of-function genetic variant in ATG16L1 (autophagy related 16 like 1) is associated with risk for developing Crohn disease (CD)." (PMID 41382985, 2026). "Mice with mutations in the Crohn's disease susceptibility gene Atg16l1 are susceptible to inflammation associated with intestinal epithelial cell (IEC) death, including loss of antimicrobial Paneth cells triggered by infection with murine norovirus (MNV)." (PMID 41648406, 2026). "The ATG16L1 T300A variant impairs the clearance of adherent-invasive Escherichia coli (AIEC)—a bacterium enriched in Crohn’s disease—highlighting a key role for autophagy in microbial defense." (PMID 40649913, 2025). "Previous studies reported that the dysfunctional Thr300Ala variant of ATG16L1 is associated with enhanced survival in patients with Crohn’s disease and CRC." (PMID 41057521, 2025). "Despite extensive genome-wide association studies identifying over 200 loci associated with IBD, such as NOD2, ATG16L1, and IL-23R, these genetic variants account for only a fraction of the heritability observed in Crohn’s disease (CD) and UC." (PMID 41007813, 2025). "Over the past two decades, research into the role of autophagy in gut health has grown significantly, stemming from landmark discoveries that uncovered polymorphisms in the core autophagy gene ATG16L1 (autophagy-related-16-like 1) linked to Crohn’s disease." (PMID 40395982, 2025). "NOD2, the strongest genetic risk factor for Crohn’s disease, interacts with ATG16L1 and is crucial for antimicrobial autophagy in phagocytes." (PMID 40649913, 2025). "Crohn disease-associated variants in ATG16L1, IRGM, and NOD2 are linked with a defect in autophagy-mediated AIEC clearance accompanied by enhanced pro-inflammatory cytokine production in epithelial cells and macrophages." (PMID 40910070, 2025). "Our data from genetically modified mice now provide evidence for the role of the Crohn’s disease risk gene ATG16L1 in intestinal epithelial cells (IECs) in this process." (PMID 39620359, 2024). "Lassen and coauthors demonstrated ATG16L1 Thr300Ala knock-in mice confer morphological abnormalities in Paneth and goblet cells associated with Crohn's disease." (PMID 38741166, 2024). "Here, we explored the longitudinal dynamics of gut microbiota composition and functional potential during pregnancy and after lactation in Atg16l1∆IEC mice carrying an intestinal epithelial deletion of the Crohn’s disease risk gene Atg16l1." (PMID 39620359, 2024). "Correlative to this observation, histological analyses of terminal ileum of patients with Crohn’s disease with Atg16l1 deficiency indicated a reduction in API5+ γδ IEL cells." (PMID 38275765, 2024). "The presence of Crohn's disease-associated ATG16L1 (T300A) inhibits TNF and IFN-γ-induced PTPN2 protein increase." (PMID 39883213, 2024). "While CD is a heterogeneous disorder with multifactorial etiology, in which genetics and environment interact, genome-wide association studies have linked polymorphisms in the autophagy gene ATG16L1 to Crohn’s disease susceptibility." (PMID 38275765, 2024). "ATG16L1 has a SNP that causes threonine to be replaced by alanine (T300A), which has been defined as a risk allele for Crohn's disease." (PMID 39883213, 2024). "Together with ATG16L1, another susceptibility locus for Crohn’s disease, NOD2 triggers the process of autophagy by accumulating at the site where bacteria gather." (PMID 39095853, 2024).
Crohn disease (continued). "Variants within the autophagy gene ATG16L1 have been implicated in susceptibility and severity of Crohn’s disease (CD)." (PMID 39464882, 2024). "A follow-up study revealed that macrophages isolated from patients carrying the Crohn's disease-associated ATG16L1 mutant T300A produced more IFN-β when stimulated with the ligand poly (I: C) for TLR3 and the ligand LPS for TLR4." (PMID 39883213, 2024). "In contrast, genetic variants of the ATG16L1 gene are some of the most studied in the pathogenesis of Crohn’s disease, playing a role in pathogen clearance, cytokine production, protein regulation and endoplasmic stress response control." (PMID 38060592, 2023). "In this study, we leveraged GWAS of inflammatory bowel disease to focus on ATG16L1, a gene highly associated with intestinal inflammation in Crohn’s disease." (PMID 37741832, 2023). "The rs2241880 (A>G) was associated with Crohn’s disease in different populations, as ATG16L1 regulates the specialised Paneth cells of the epithelium of the small intestine." (PMID 38136993, 2023). "Patients with a major type of IBD called Crohn’s disease who are homozygous for the T300A variant of ATG16L1 display morphologically aberrant Paneth cells, which is reproduced in mice harboring mutations in various autophagy genes." (PMID 37425656, 2022). "Common intronic variants of ATG16L1 were previously found to be associated with Crohn’s disease, inflammatory bowel disease, and increased bilirubin levels." (PMID 36088354, 2022). "Of note, polymorphisms in both NOD2 and ATG16L1 are associated with Crohn’s disease, a severe inflammatory bowel disease." (PMID 37425656, 2022). "Persistent norovirus infection followed by DSS treatment in mice harbouring a mutation in Atg16L1, a Crohn’s disease susceptibility gene, resulted in inflammation and hallmarks of Crohn’s disease." (PMID 35737518, 2022). "In humans, 16 different single nucleotide variants (SNPs) located within the Atg16l1 gene and in an intergenic region between the Atg16l1 and Scarna5 genes have been associated with inflammatory bowel disease, ulcerative colitis, and Crohn’s disease." (PMID 35509963, 2022). "Our results indicate that the ATG16L1 T300A Crohn's disease-associated SNP causes a decrease in migration capacity in epithelial cells, mediated by an increase in SQSTM1 and ARHGAP18 protein and subsequent reduced RhoA activation." (PMID 33973626, 2021). "African-Americans trend to express the ATG16L1 T300 isoform compared to Europeans who express the ATG16L1 A300 isoform and this is causal in European Americans presenting with higher levels of Crohn’s Disease than African Americans." (PMID 34252884, 2021). "The polymorphisms in human ATG16L1 have been associated with an increased risk of Crohn’s disease, a well-known autoinflammatory disorder." (PMID 34208077, 2021). "Loss-of-function of the core autophagy gene Atg16l1 increases risk for Crohn’s disease in part by enhancing innate immunity through myeloid cells such as macrophages." (PMID 34085925, 2021). "Consistent with our results, NOD2 expression is significantly increased in IBD, and the excessive expression of NOD2 causes impaired autophagy through activation of ATG16L1, thus resulting in cell death in Crohn’s disease." (PMID 33670592, 2021). "The ATG16L1 T300A single-nucleotide polymorphism (SNP) is associated with Crohn's disease and causes an autophagy impairment." (PMID 33973626, 2021). "According to a previous study, the G allele of ATG16L1 rs2241880 was significant in susceptibility to other autoinflammatory diseases, such as Crohn’s disease." (PMID 34208077, 2021). "Biopsies from patients with Crohn’s disease showed that ATG16L1 with the T300A mutation increases susceptibility to H. pylori infection, indicating that the ATG16L1 genotype modulates autophagy responses to VacA." (PMID 34439541, 2021).
Crohn disease (continued). "The ATG16L1T300A polymorphism is associated with Crohn’s disease, and ATG16L1 has an important role in Paneth cell survival and function." (PMID 32671059, 2020). "SA is triggered by bacteria-induced ER stress and it is disrupted in Paneth cells of mice harboring ATG16L1, which is a variant of ATG16L related to high risk for Crohn's disease." (PMID 32477265, 2020). "Nod2 polymorphism is also a risk factor for Crohn’s disease, and Nod2 and Atg16L1 work cooperatively in bactericidal autophagy." (PMID 31932716, 2020). "Although, until recently, Atg16L1 mutants have only been associated and thoroughly investigated in the context of Crohn’s disease, new information regarding ATG16L1 implications in UC pathology started to be of interest for researchers." (PMID 32659925, 2020). "For example, mutations in the Crohn’s Disease susceptibility genes, Atg16l1 and Xbp1 result in abnormal granule morphology and reduced numbers of granules in Paneth cells both in genetically deficient mice and in Crohn’s disease patients." (PMID 30804449, 2019). "In mice, the mutations that eliminated or reduced Atg16L1 expression indicated a relationship between Atg16L1 mutations and Crohn’s disease." (PMID 31277291, 2019). "A study on the 300T > A Atg16L1 mutation revealed that the mutation is differentially involved in Crohn’s disease and canonical autophagy." (PMID 31277291, 2019). "Among intestinal diseases, autophagy was first linked to pathogenesis of Crohn’s disease when genome-wide association studies identified mutations in the autophagy-related gene ATG16L1 as a risk factor for Crohn’s disease." (PMID 31683886, 2019). "For example, mice with a hypomorphic mutation in the autophagy gene Atg16L1, which is a susceptibility gene in Crohn’s disease, show Paneth cell abnormalities leading to defective antibacterial defense and a hyperinflammatory state in the intestine." (PMID 29570694, 2018). "Gene‐gene interaction analysis revealed significant interactions between MST1 and other susceptibility genes, including NOD2, MUC19 and ATG16L1 in contributing to Crohn's disease risk." (PMID 29441677, 2018). "Paneth cell dysfunction is associated with Crohn’s disease and is linked to the presence of risk alleles for an autophagy gene ATG16L1." (PMID 29454391, 2018). "In Crohn’s disease, many associations with autophagy-related genes, such as ATG16L1, IRGM, NOD2, and others, have been reported." (PMID 30583538, 2018). "Autophagy-related 16-like 1 (Atg16L1), a gene essential for functional autophagosome, has been implicated in Crohn’s disease." (PMID 28498331, 2017). "ATG16L1 is a master regulator of the core autophagy machinery that was initially identified as a pivotal risk factor for Crohn’s disease." (PMID 27128681, 2016). "The Crohn’s disease associated ATG16L1 coding variant shows impairment of the capture of internalized Salmonella within autophagosomes." (PMID 26893616, 2016). "A coding polymorphism of human ATG16L1 (rs2241880; T300A) increases the risk of Crohn's disease and it has been shown to enhance susceptibility of ATG16L1 to caspase cleavage." (PMID 27273576, 2016). "Although ATG16L1 (T300A) was found in Asian populations, the relationship of the variants and Asian Crohn's disease is still to be confirmed." (PMID 25883416, 2015). "GWAS have implicated several autophagy genes, including Atg16l1, Lrrk2, and Irgm in the genetic susceptibility to Crohn's disease." (PMID 26484345, 2015). "Regarding genes involved in autophagy, we have chosen IRGM and ATG16L1 as candidate genes, since they were associated with Crohn's disease." (PMID 25369137, 2014). "A link between NOD2 and ATG16L1 as presented in this model is of great fundamental importance, because SNPs in both proteins are implicated in Crohn's disease and hamper autophagy induction." (PMID 25520185, 2014).
Crohn disease (continued). "The association between Crohn's disease and ATG16L1 polymorphisms ignited further investigations regarding the regulation of the inflammatory response by autophagic machinery." (PMID 24818040, 2014). "A strong genetic link was recently described between the autophagy gene ATG16L1 and susceptibility to chronic inflammation in Crohn disease." (PMID 24356959, 2014). "One example is studies on the role of autophagy related 16-like 1 (Saccharomyces cerevisiae) (ATG16L1) in the risk of Crohn's disease." (PMID 23982303, 2014). "Cells obtained from Crohn's disease patients with the ATG16L1 (T300A) polymorphism have decreased autophagic activity following exposure to muramyl dipeptides." (PMID 24818040, 2014). "Another autophagy gene associated with autoimmunity is Atg16l1, being implicated in Crohn’s disease (CD)." (PMID 23596443, 2013). "The role of NOD1 and 2 in this process was initially proposed following GWAS findings of an association between a key component of the autophagy process, ATG16L1, and susceptibility to Crohn’s disease." (PMID 24137163, 2013). "Dendritic cells from individuals with Crohn's disease that express NOD2 or Atg16L1 risk variants perform defective autophagy." (PMID 22110539, 2012). "The first indication that the autophagy pathway contributes to Crohn’s disease came from three GWAS published close together that implicated a common Threonine to Alanine substitution (T300A) in ATG16L1." (PMID 21994779, 2011). "One possible explanation for the involvement of defective autophagy in Crohn's disease inflammation couples the risk alleles in ATG16L1 and NOD2 (nucleotide-binding oligomerization domain containing 2) to an impaired clearance of microorganisms." (PMID 21490934, 2011). "ATG16L1-deficient Paneth cells exhibited abnormalities in the granule exocytosis pathway, a feature that was common to Crohn's disease patients that were homozygous for the ATG16L1 disease risk allele." (PMID 20808783, 2010). "Here we report that, in human epithelial cells, the Crohn's disease-associated ATG16L1 coding variant shows impairment in the capture of internalized Salmonella within autophagosomes." (PMID 18852889, 2008). "Indeed, studies with both Atg16L1 mutant mice and Crohn’s disease patients carrying the ATG16L1 risk allele show morphological defects in Paneth cells." (PMID 40002565, 2025). "In addition, a variant of ATG16L1, a gene involved in cellular autophagy, has been associated with increased susceptibility to Crohn’s disease." (PMID 40002565, 2025). "In addition to immune cells, ATG16L1-mediated autophagy contributes to distinct functions within various epithelial cell lineages that impact protection and susceptibility to Crohn disease." (PMID 40910070, 2025). "The first autophagy gene to be associated with Crohn disease was ATG16L1." (PMID 40910070, 2025). "The ATG16L1 Thr300Ala polymorphism is connected to a heightened susceptibility to Crohn's disease." (PMID 38741166, 2024). "The Crohn's disease-related ATG16L1 mutation T300A disrupts intestinal immune homeostasis by diminishing AMPs production in Paneth cells and over-secretion of the pattern recognition receptors (PRRs)-mediated pro-inflammatory cytokines by dendritic cells (DCs) and macrophages." (PMID 39883213, 2024). "Furthermore, it was discovered that the DCs derived from Crohn's disease patients who expressed NOD2 or ATG16L1 risk alleles associated with the disease were impaired in antigen presentation, bacterial transport, and autophagy induction." (PMID 39883213, 2024). "Notably, the ATG16L1 T300A Crohn’s disease variant associated with dysfunctional autophagy flux is known to impact Th1 responses as well as IL-1β-secretion." (PMID 38548722, 2024). "Also, Atg16L1 mutation increased the phagocytosis ability of monocytes isolated from Crohn’s disease patients." (PMID 36451006, 2023).